BCL10 (BCL10 immune signaling adaptor)
Diseases named in the same sentence as BCL10 in open-access papers (continued):
Sharing a sentence is not in itself a finding about the gene and the disease.
Obesity (5 papers, 2017 to 2025). Accumulation of substantial excess body fat. "HFD/obesity‐induced expression of both BCL10 and CARD9 further increased due to zinc deficiency." (PMID 28158919, 2017). "Furthermore, CARD9/BCL10 may be implicated in the synergistic effects of MT-KO and obesity on cardiac remodeling." (PMID 39897024, 2025). "We previously reported the regulation of CARD9 and BCL10 expression in the hearts of mice with obesity and diabetic cardiomyopathy." (PMID 39897024, 2025). "We observed that obesity induces cardiac hypertrophy by activating p38 MAPK through CARD9/BCL10 complex upregulation, which was assumed to be mediated by increased oxidative stress 10,19." (PMID 39897024, 2025). "CAST Tg overexpression mediated calpain inhibition significantly suppressed obesity induced apoptotic cell death, pro-apoptotic genes (Bid, Bax, and Bcl10), and adipose tissue macrophage accumulation." (PMID 29089532, 2017). "We hypothesize that obesity activates p38 MAPK pathway through the upregulation of Bcl10/CARD9 complex." (PMID 28158919, 2017). "MT-KO combined with HFD-induced obesity synergistically promotes cardiac remodeling, possibly via trace metal dyshomeostasis-induced oxidative stress to trigger CARD9/BCL10-mediated NF-κB activation." (PMID 39897024, 2025). "Here our in vivo data suggest that CARD9/BCL10 may activate NF-κB, but not MAPKs, to mediate obesity- or MT-induced cardiac inflammation." (PMID 39897024, 2025).
malignant melanoma (4 papers, 2019 to 2025). "In malignant melanoma models, acute genetic blockade of BCL10 signaling selectively in Tregs or pharmacological MALT1 inhibition enhances anti-tumor immune responses." (PMID 31138793, 2019). "The interaction among CARMA1, BCL10, and MALT1 also affects the activity of downstream NK-KB signaling pathway, and the control of BCL10 on MALT1 paracaspase activity affects the formation of malignant melanoma TME." (PMID 35927985, 2022). "BCL10 (3.84-fold), TRADD (2.71-fold), CYCS (2.51-fold), DIABLO (2.43-fold), BAD (2.36-fold), BID (2.17-fold), TNFSF8 (2.13-fold), TNFSF10 (2.11-fold), BAX (2.03-fold), and FAS (2.01-fold) were also proapoptotic genes highly upregulated in response to UA treatment in A-375 melanoma cells." (PMID 39473730, 2024).
acinar cell carcinoma (3 papers, 2016 to 2025). "The tumor was diagnosed as acinar cell carcinoma since immunohistochemical examination showed tumor cells positive for BCL10, lipase, and trypsin." (PMID 41159018, 2025). "Ancillary testing performed on the cytologic material may help to additionally reach a specific malignant diagnosis; for instance, BCL-10 immunopositivity supports the diagnosis of acinar cell carcinoma, while specific IHC panels may help identify PDAC variants or metastases to the pancreas." (PMID 35163571, 2022).
asthma (3 papers, 2020 to 2023). "Bcl10 signaling plays an important role in establishing the inflammatory environment associated with asthma." (PMID 35885021, 2022). "Here, we showed that Bcl10 mediated the LPS-induced expression of IL-6, IL-8 and TGF-β1 in bronchial fibroblasts, highlighting the pathogenic role of Bcl10-mediated signaling in promoting airway remodeling in severe asthma." (PMID 35885021, 2022). "We screened seven candidate diagnostic biomarkers for asthma using LASSO regression (namely, BCL10, CD300E, IER2, MMP13, OAF, TBC1D3, and TMEM151A), among which the area under the curve (AUC) value for CD300E and IER2 were 0.722 and 0.856, respectively." (PMID 37259023, 2023). "Taken together, these findings confirm constitutively higher Bcl10 expression in asthma, particularly in severe asthma, and its localization predominantly in the cytoplasmic compartment in bronchial fibroblasts." (PMID 35885021, 2022). "Biopsies from mild and moderate cases of asthma displayed moderate Bcl10 expression in both the epithelium and subepithelium with very few subepithelial fibroblasts staining positively for Bcl10." (PMID 35885021, 2022). "Bcl10 being a critical mediator of NF-κB signaling prompted us to explore its role in fibrotic remodeling in bronchial fibroblasts from severe asthma." (PMID 35885021, 2022). "We identified the Bcl10-mediated NF-κB pathway as a mechanism contributing to fibrotic remodeling and inflammation in severe asthma." (PMID 35885021, 2022). "In order to validate the increased protein expression of Bcl10 in severe asthma, we evaluated its immunohistochemical expression and distribution in bronchial biopsies obtained from normal individuals and asthma patients of varying severities." (PMID 35885021, 2022). "NF-κB activation is increasingly recognized in the pathogenesis of asthma and Bcl10-mediated NF-κB signaling has widely been studied as an inflammatory pathway in immune cells." (PMID 35885021, 2022). "Bcl10 protein was variably expressed in the airways of both normal and asthma patients." (PMID 35885021, 2022). "Thus, the increased Bcl10 expression in S-As fibroblasts appears to signify the activation of the Bcl10-mediated NF-κB pathway in severe asthma." (PMID 35885021, 2022). "Bcl10 may serve as a potential biomarker for testing the activation of NF-kB pathway in asthmatic patients and for asthma targeted therapy, taking into account its role in both airway inflammation and remodeling." (PMID 35885021, 2022). "This allows us to selectively target Bcl10 to impede its pathological signaling in severe asthma." (PMID 35885021, 2022). "However, the role of Bcl10-driven NF-κB activation is yet to be explored in the context of airway remodeling in asthma." (PMID 35885021, 2022). "Furthermore, Bcl10 immunoreactivity in the subepithelium of airway tissues varied in intensity and distribution with increasing severity of asthma, relaying its importance in asthma severity." (PMID 35885021, 2022). "Furthermore, Bcl10 was differentially expressed in the sub-epithelial fibroblasts among the varying severities of asthma, ranging from weak expression in control biopsies to moderate expression in mild-to-moderate asthma and strong expression in severe asthma." (PMID 35885021, 2022). "Both BCL-10 and IFNB1 are known to be associated with asthma status." (PMID 32900903, 2020). "Thus, the presence of Bcl10 in the cytoplasmic compartment of S-As fibroblasts may signify its role in regulating actin dynamics and contraction of bronchial fibroblasts, and by this means, contributing to airway hyperresponsiveness in severe asthma." (PMID 35885021, 2022). "Drug (entinostat, BMS-345541) and genetic perturbagens (KLF6, BCL10, INFB1 and BAMBI) negatively connected to disease at multi-tissue level could potentially repurposed for treating asthma." (PMID 32900903, 2020).
cardiac hypertrophy (3 papers, 2017 to 2024). "Zinc supplementation can prevent obesity-related cardiac hypertrophy in a mouse model by inhibiting CARD9/BCL10 signaling." (PMID 35173530, 2022). "In conclusion, we demonstrate that zinc plays a critical role in modulating the expression of BCL10 and CARD9 associated by HFD, which stimulated p38 MAPK phosphorylation and p38 MAPK‐mediated cardiac hypertrophy signalling." (PMID 28158919, 2017). "Taken together, we conclude that BCL10 is an important mediator of p38 MAPK activation to induce cardiac hypertrophy under obese conditions with or without zinc deficiency." (PMID 28158919, 2017). "Therefore, our findings support the hypothesis that activation of BCL10/CARD9/p38 MAPK‐mediated cardiac hypertrophy pathways plays an important role in the development of ORCH." (PMID 28158919, 2017). "Furthermore, they support a model where BCL10 and CARD9 are upstream of p38 MAPK, and that their interaction directly activates p38 MAPK to promote cardiac hypertrophy." (PMID 28158919, 2017).
Insulin resistance (3 papers, 2013 to 2024). Increased resistance towards insulin, that is, diminished effectiveness of insulin in reducing blood glucose levels. "Other recent work has identified Bcl10 as a link between fat (palmitate) intake and hepatic NF-κB activation and insulin resistance, and Bcl10 was reported to coordinate the NF-κB-mediated response associated with endosomal trafficking and F-actin remodeling in human macrophages." (PMID 23766559, 2013).
ovarian carcinoma (3 papers, 2015 to 2021). A malignant neoplasm originating from the surface ovarian epithelium. "MiR-106a and miR-591 have important roles in conferring paclitaxel resistance to ovarian cancer cells, and modulating miRNAs to resensitize paclitaxel-resistant cancer cells by regulating BCL10, caspase-7, and ZEB1." (PMID 25887170, 2015).
pancreatic acinar cell carcinoma (3 papers, 2021 to 2025). An adenocarcinoma arising from the pancreas. "Studies are needed to investigate whether the additional use of CELA3B will increase the diagnostic precision that can be achieved by using CPA1, chymotrypsin, trypsin, or bcl10 for diagnosing acinar cell carcinoma of the pancreas." (PMID 37379306, 2023). "However, little is known about the biological characteristics of BCL10 in PDAC, although the expression of BCL10 has previously been reported in pancreatic acinar cell cancer." (PMID 34412631, 2021).
prostate carcinoma (3 papers, 1999 to 2025). A carcinoma that arises from epithelial cells of the prostate gland. "We have used single-strand conformation polymorphism (SSCP) analysis to screen for mutations in the BCL10 gene in 81 primary prostate carcinomas, 20 squamous cell cancers of the head and neck, 15 small-cell lung cancer cell lines, 24 renal carcinoma cell lines and 13 sarcoma cell lines." (PMID 10408398, 1999).
psoriasis (3 papers, 2017 to 2024). An autoimmune condition characterized by red, well-delineated plaques with silvery scales that are usually on the extensor surfaces and scalp. "The activation of NF-κB by gain-of-function psoriasis-associated CARD14 mutants involves CARD14 forming a complex with BCL10 and MALT1." (PMID 39145956, 2024). "Although it is known that psoriasis-associated CARD14 mutations induce the association of CARD14 with BCL10 and MALT1, knowledge about the signalling proteins and pathways involved in CARD14 signalling is rather limited." (PMID 39145956, 2024). "We also show that at least three CARMA2sh mutants associated with genetic psoriasis fail to promote degradation of BCL10, despite being phosphorylated by ULK2." (PMID 28230860, 2017). "The NF-κB-inducing activity of both wt- and psoriasis-linked CARMA2sh mutants requires BCL10, as assessed by experiments based on shRNA-mediated depletion of BCL10 and disruption of the BCL10 locus through CRISPR/Cas9/sgRNA technology in HEK293T cells." (PMID 28230860, 2017). "Degradation of BCL10 by ULK2 requires phosphorylation of CARMA2sh, and is prevented by several psoriasis-linked CARMA2sh mutations." (PMID 28230860, 2017). "Psoriasis-associated mutations in CARD14 similarly cluster within the CARD and CC domains and we have recently demonstrated that the highly penetrant CARD14E138A psoriasis-associated mutation induces a conformational change in CARD14 that induces interaction with BCL10 and MALT1." (PMID 39145956, 2024). "Altogether, these data indicate that ULK2-mediated lysosomal degradation of BCL10 represents an intrinsic homeostatic mechanism that restricts NF-κB signaling in keratinocytes, and the psoriasis-linked CARMA2sh mutants we tested failed to promote such a constraining mechanism." (PMID 28230860, 2017). "Therefore, the inhibition of BCL10 may represent a potentially novel therapeutic method for different CB-SMOC-dependent disease conditions, ranging from ABC-DLBCL and other aggressive cancers to inflammatory diseases such as psoriasis." (PMID 33052237, 2020).
Stroke (3 papers, 2020 to 2024). Sudden impairment of blood flow to a part of the brain due to occlusion or rupture of an artery to the brain. "Calcium signaling pathway-related genes (AC079305.10, BCL10, BCL2A1, BRE-AS1, DYNLL2, EREG, and PTGS2) are related to apoptosis after stroke, whereas posttranscriptional regulation of BCL2A1 may be possibly associated with IS." (PMID 34987704, 2021).
viral infections (3 papers, 2014 to 2023). "CARD9 is expressed in myeloid cells, MΦs, and DCs, and CARD9 complexes with BCL10 and MALT1 contribute to innate and adaptive immune responses to viral infections." (PMID 37334361, 2023). "Furthermore, since Bcl10 inhibition was not accompanied by alterations in the TRIF-dependent induction of type I interferons, anti-viral signaling and immune defense against viral infections will be sustained in these cells." (PMID 35885021, 2022).
B-cell CLL (2 papers, 2012 to 2022). "A total of 16 GO terms were enriched for down-regulated NSDEGs, including cfi (complement factor I) and bcl10 (B-cell CLL/lymphoma 10), and the most significant GO term was “MHC class II protein complex” related to immune response." (PMID 35669183, 2022).
cervical cancer (2 papers, 2019 to 2021). A primary or metastatic malignant neoplasm involving the cervix. "Consistent with this, BCL10 controls the growth of cervical cancer cells via NF-κB-dependent cyclin D1 regulation in cervical cancer cells." (PMID 31658764, 2019). "BCL10-related signaling controls the growth of cervical cancer cells via NF-κB-dependent cyclin D1 regulation." (PMID 31658764, 2019). "Furthermore, we reported that BCL10 regulates tumor cell growth of cervical cancer cells by regulating the activation of NF-κB-dependent Cyclin D1 signaling." (PMID 34412631, 2021).
colitis (2 papers, 2017 to 2025). Inflammation of the colon. "In murine models, carrageenan administration (e.g., 10–50 mg/kg/day via drinking water) induces colitis, with significantly reduced severity observed in Bcl10-deficient mice, underscoring the role of the Bcl10–NF-κB pathway in mediating inflammation." (PMID 41470798, 2025).
leukemia (2 papers, 2018 to 2024). A malignant (clonal) hematologic disorder, involving hematopoietic stem cells and characterized by the presence of primitive or atypical myeloid or lymphoid cells in the bone marrow and the blood. "As immune disease-related genes, MYD88 (81.4%) and BCL10 (25.9%) in NF-ĸB signaling, CD79B (59.2%), PAX5 (22.2%), and BCR (7.4%) in B-cell development, and MYH11 (25.9%), RUNX1 (7.4%), and TET2 (7.4%) in leukemia were observed." (PMID 29937999, 2018).
lung carcinoma (2 papers, 2012 to 2025). "CARMA3- or Bcl10-targeting siRNAs led to a clear reduction of the colony formation capacity of two tested lung cancer cell lines compared to control siRNA-treated cells." (PMID 22615840, 2012). "We utilized an independent method, colony formation assays, to validate the anti-proliferative effects of CARMA3 or Bcl10 inhibition in lung cancer cells." (PMID 22615840, 2012). "It was also noteworthy that a recent preclinical study demonstrated that EEF1A2 knockdown suppresses lung cancer brain metastasis by inhibiting the BCL10/NFκB pathway and reversing EMT, further validating the therapeutic potential of targeting eEF1A isoforms in advanced cancers." (PMID 40806463, 2025).
mantle cell lymphoma (2 papers, 2024 to 2025). Mantle cell lymphoma is a rare form of malignant non-Hodgkin lymphoma affecting B lymphocytes in the lymph nodes in a region called the ``mantle zone''. "MALT1i-BTKi combinations showed promise in mantle cell lymphoma, but we were underwhelmed by the combination in BCL10-mutant DLBCL systems." (PMID 39894894, 2025).
sarcoma (2 papers, 1999 to 2024). A usually aggressive malignant neoplasm of the soft tissue or bone. "In cellular experiments, we observed significantly upregulated mRNA expression of CALR, CASP3, BCL10, PSMD7, and PSMD10 in sarcoma cell lines compared to their corresponding normal cell lines." (PMID 39469643, 2024).
Sepsis (2 papers, 2022 to 2025). Sepsis is defined as life-threatening organ dysfunction caused by a dysregulated host response to infection. "The conduct of this study provides new clues for the translational research of Emodin and its target BCL‐10 in sepsis." (PMID 40779122, 2025). "Emodin effectively targets BCL‐10 to inhibit NF‐κB activation, thereby reducing NETs formation, highlighting its therapeutic potential in sepsis." (PMID 40779122, 2025). "In summary, these results suggest that neutrophil hyperactivation, NETs formation, and high BCL‐10 expression are central to sepsis pathogenesis." (PMID 40779122, 2025). "BCL‐10 may serve as a regulatory gene promoting NETs formation, with Emodin potentially mitigating sepsis by targeting BCL‐10 and inhibiting NETs formation." (PMID 40779122, 2025). "Importantly, we also found that the selective depletion of BCL‐10 in neutrophils significantly mitigates sepsis‐induced organ damage and NETs formation." (PMID 40779122, 2025). "Finally, while this work centers on the BCL‐10/NETosis regulatory axis, sepsis pathogenesis inherently involves dynamic interplay among inflammatory activation, coagulation disorders, immune suppression, and metabolic dysregulation." (PMID 40779122, 2025). "Furthermore, we found that Emodin exerts its protective effects in sepsis by targeting and inhibiting BCL‐10, which modulates nuclear factor kappa‐light‐chain‐enhancer of activated B cells (NF‐κB) activity, thus providing a crucial mechanism for sepsis intervention." (PMID 40779122, 2025). "Therefore, effectively inhibiting NET formation through targeting the BCL‐10/NF‐κB axis may provide a critical therapeutic strategy for alleviating coagulation dysfunction in sepsis." (PMID 40779122, 2025). "Collectively, these findings provide pharmacological evidence that Emodin targeted BCL‐10 regulates the BCL‐10/MALT1 complex and suppresses NF‐κB activation, ultimately conferring significant multiorgan protective effects in sepsis." (PMID 40779122, 2025). "Emodin targets BCL‐10 to modulate the BCL‐10/MALT1 complex, thereby suppressing NF‐κB activation and significantly exerting multiorgan protective effects in sepsis." (PMID 40779122, 2025). "Immunofluorescence confirmed the colocalization of the BCL‐10‐MALT1 complex, indicating that elevated BCL‐10 protein activates NF‐κB signaling through the BCL‐10‐MALT1 complex, promoting NETs formation during sepsis." (PMID 40779122, 2025). "Through conditional knockout of BCL‐10 in neutrophils, alongside single‐cell sequencing analyses, it is confirmed that BCL‐10 is key in promoting excessive NET formation in sepsis." (PMID 40779122, 2025). "To further investigate the role of BCL‐10 in sepsis, we crossed BCL‐10flox/flox mice with mRP8‐Cre mice to generate a neutrophil‐specific BCL‐10 knockout model: mRP8‐Cre BCL‐10flox/flox (BCL‐10−/−) mice and BCL‐10flox/flox (BCL‐10f/f) mice, for studying the function of BCL‐10 in sepsis." (PMID 40779122, 2025).
T-cell lymphomas (2 papers, 2007 to 2015). "Our results demonstrate interplay between CAV1 and BCL10 in T-cell lymphomas and warrants further investigation." (PMID 26566034, 2015). "BCL10 has been prior described as down-regulated among T-cell lymphomas, an observation in accordance with our findings." (PMID 26566034, 2015). "It is well established that in both T and B cells, BCL10 specifically mediate antigen receptor-induced NF-κB activation In NK cells, BCL10 has been observed in the cytoplasm of normal NK cells, and in the nuclei of tumor cells of nasal NK/T-cell lymphomas." (PMID 17623099, 2007).
adenosquamous carcinoma (1 paper, 2024). A carcinoma composed of malignant glandular cells and malignant squamous cells. "BCL10 is exclusively expressed in normal acini and shows positive expression in 82% of resected ACC cases and 50% of adenosquamous carcinoma cases, while exhibiting negative expression in other subtypes of pancreas neoplasms." (PMID 38625458, 2024).
alcoholism (1 paper, 2021). "The difference in the demography, including age, sex, smoking history, and alcoholism were not significant between patients with nuclear BCL10 expression in tumors and those without nuclear BCL10 expression in tumors." (PMID 34412631, 2021).